CD28 (CD28 molecule)
Diseases named in the same sentence as CD28 in open-access papers (continued):
Sharing a sentence is not in itself a finding about the gene and the disease.
tumor (continued). "CD28 co-stimulation may be more beneficial for other tumour models, where the microenvironment and the exhaustion of T cells are important factors for tumour lysis efficacy." (PMID 37591933, 2023). "However, in the LY2 model, IL-10 was higher in lymph node cells stimulated with the IR tumor antigen compared to CD3/CD28 antibody stimulation." (PMID 37444444, 2023). "A PD‐1 CD28 CAR structure consisting of a PD1 extracellular domain recognizing PDL‐1 expressed on tumor cells was established along with a TM, and a cytoplasmic domain of CD28 transducing activation signaling, which transduces an activating signal after reacting with PDL‐1 on the tumor cell." (PMID 38045827, 2023). "Therefore, we sought to investigate if SNX9 specifically affects CD28 signaling in our experimental system with primary tumor-antigen-specific T cells." (PMID 36732507, 2023). "Similarly, we observed improved T cell activity upon anti-CD3/anti-CD28 stimulation in siB3 tumor–derived CD8+ T cells, which showed a markedly higher proliferative capacity than did those derived from siNC tumors." (PMID 37279067, 2023). "Furthermore, LPPC/MP/CD28 complexes more dramatically eliminated metastatic tumor cells in the lung and stimulated more IFN-γ release than LPPC/MP complexes." (PMID 36691089, 2023). "Interestingly, in the stroma, CD8+CD28+PD-1+ T cells were also found to be closer to both tumor cells and to CD11c+CD86+ APCs in progression-free patients." (PMID 37349318, 2023). "In contrast, LPPC/MP and LPPC/MP/CD28 complexes both dramatically abolished tumor nodule formation." (PMID 36691089, 2023). "After co-incubation with tumor cells, the CD28 group showed a decreased CD39 expression for F8-FR4.V and Dual.V CAR T cells (16% ± 1% for both), while CD276.V-CARs remained at higher levels of 22% ± 5% when co-incubated with Rh4 and of 21% ± 5% when co-incubated with JR." (PMID 37924157, 2023). "However, on activated T cells, CTLA4 directly competes with CD28 for B7 ligands to mediate tumor immune responses." (PMID 37745297, 2023). "Conversely, CD80/CD86-targeted CAR-T (CTLA4-CAR), which comprises the extracellular and transmembrane portions of human CTLA4, the cytoplasmic region of human CD28, and the intracellular domains of human CD3z, was designed to destroy CD80/CD86-associated tumor cells in vitro and vivo." (PMID 37457699, 2023). "Cluster3 of both subsets (which we refer to as NK-innate-likeCD28− and CD28+, respectively), represented in peripheral blood and reduced at the tumor site, were characterized by the expression of NK-like markers KLRB1, KLRC3, and KIR2DL1, along with IKZF2 and ZBTB16 (PLZF)." (PMID 37898752, 2023). "In tumor settings, T cells could experience a phenotypic shift to terminal differentiation characterized by expressing KLRG-1 and CD57 but loss of CD28 after persistent exposure to neoantigen, which is termed “T-cell senescence”." (PMID 36960073, 2023). "In contrast CD28− TRM mainly produced CXCL13 within the tumor." (PMID 37898752, 2023). "However, a preclinical study showed that CAR T-cells with a CD28 co-stimulatory domain have a stronger anti-tumor response, and that CAR T-cells with a 4-1BB co-stimulatory domain take longer to achieve similar effects." (PMID 37345104, 2023). "While incorporating CD28 or 41BB costimulatory domains into CARs in addition to the CD3z signaling domain improved the long-term efficacy of T cell products, their influence on early tumor engagement has yet to be elucidated." (PMID 37370693, 2023). "In addition, a population of CD8+ T-cells with the suppressive phenotype (CD8+CD28−) was also detected in the tumor microenvironment." (PMID 37835465, 2023). "While CARs containing the CD28 domain generate a faster, stronger signal than those containing the 4-1BB domain, leading to a more potent target cell killing activity, CD28-CARs also demonstrated limited long-term survival and anti-tumor durability due to CAR-T cell exhaustion." (PMID 37779207, 2023).
tumor (continued). "Further, TCR repertoire spectrum typing and sequencing were important for identifying whether CD8+CD28− T cells could recognize tumor antigens." (PMID 35480107, 2022). "The differences in the tumor model (Nalm6 versus Namalwa) as well as in the CAR signaling domain (CD28 versus 4-1BB) and scFv (FMC63 versus A3B1) could explain the observed differences." (PMID 35694446, 2022). "It was found that CD28 activated T cells had a strong instantaneous mortality, while 4-1BB activated T cells had better anti-tumor persistence.The intracellular portion of third-generation CAR-T cells contains two costimulatory molecules(CD28 and 4-1BB) in order to enhance activation of T cells." (PMID 35860578, 2022). "Thus, by removing sialic acid ligands on the surface of tumor cells, CD28 is better able to engage CD80, accounting for increased co-stimulation of T cells." (PMID 36316782, 2022). "We found that activated (CD3/CD28 + hIL-2 cocktail) PBMCs, primed with galanin, significantly enhanced tumor growth compared to UM-SCC-29 cells alone or UM-SCC-29 cells co-grafted with activated PBMCs, supporting the notion that immunomodulation by galanin favors tumor growth." (PMID 35267186, 2022). "One CAR contained T cell-specific domains with transmembrane and costimulatory domains derived from CD28 sequences and CD3ζ as the signaling domain (CD3ζ CAR), as CD3ζ has been shown to be functional in the context of CAR MΦs designed to target other tumor-associated antigens (TAA)." (PMID 35326445, 2022). "Moreover, CD28 co-stimulatory pathway plays key roles in modulating the tumor immune microenvironment and patients’ responses to anti–PD-L1/PD-1 therapy." (PMID 36171879, 2022). "CAR are synthetic receptors that consist of an MHC-independent antigen binding domain usually derived from a tumor-specific monoclonal antibody fused to an intracellular signaling region, composed of the CD3ζ chain and costimulatory molecules from CD28 and 4-1BB." (PMID 35681548, 2022). "Previous studies have suggested that exhausted, antigen-experienced CD8+ Tem cells within tumor may be derived from TCF1+CD28+ stem-like T cell (Tscm) precursors that localize to antigen presenting cell-rich niches within tumors." (PMID 36185254, 2022). "We hypothesized that ALPN-202 was unable to induce CD28 costimulation in this model because of its inability to bind mouse PD-L1 and thus the anti-tumor activity was only due to ALPN-202’s ability to bind and block CTLA-4." (PMID 35379805, 2022). "Limited GRP78-CAR T cell persistence, which was responsible for tumor recurrences, may be attributed to the CD28 costimulatory domain of our GRP78-CAR54." (PMID 35102167, 2022). "Because ALPN-202 does not block the mouse PD-1–PD-L1 interaction, we sought to understand how hPD-L1-mediated CD28 costimulation would compare to or work in combination with mPD-1 blockade in two separate tumor models: MC38/hPD-L1 and the more immunotherapy-resistant B16-F10/hPD-L1." (PMID 35379805, 2022). "Thus, it is possible that a higher sCTLA‐4 level inhibits the activation of potent antitumor T cells by blocking B7/CD28 interactions, which in turn helps the residual tumor to grow and increases the incidence of local recurrence." (PMID 35435327, 2022). "However, when co-cultured with A549 cells, HER2.28ζ CAR-T cells showed significantly higher cytotoxicity compared to HER2.BBζ CAR-T cells, indicating superior anti-tumor activity of CD28 co-stimulated CAR-T cells." (PMID 36402752, 2022). "Furthermore, CD28-costimulated MSLN CAR T cells displayed enhanced cytolytic capacity against tumor spheroids with heterogeneous MSLN expression compared to MBBz CAR T cells." (PMID 35898704, 2022). "We armored 28z CAR-T cells (CD28 co-stimulator) with IL-7 to enhance cell proliferation and effector functions, which could improve tumor cell elimination." (PMID 35869100, 2022).
tumor (continued). "Bispecific antibodies inhibited tumor growth in mice inoculated with B16 melanoma cells, resulting in the long-term survival of animals, while a second bispecific antibody that triggered the co-stimulatory CD28-molecule on the T-cell surface further increased tumor-cell killing in vitro and in vivo." (PMID 35538491, 2022). "These ineffective synapses include inactive T-cells bound in synapse through the CD28 arm, which cannot lead to T-cell activation or tumor killing, or tumor cells synapsed with other tumor or PBMCs, which again cannot promote tumor killing or T-cell activation." (PMID 35768621, 2022). "CD28-based CAR-T cells often show rapid tumor eradiation with less persistence." (PMID 35252208, 2022). "Additionally, the construction with CD28 was extremely efficient in avoiding tumor dissemination, as only one animal had a tumor with localized invasion of the diaphragm, and diminished PD-L1 and Ki67 expression by the tumor." (PMID 35628256, 2022). "However, most tumor cells can inhibit the activation of T cells by down-regulating which the expression of CD28 to achieve immune escape in TME." (PMID 36505767, 2022). "These included key genes associated with cytotoxic anti-tumor T cell responses (GZMA, GZMB, PRF1), co-stimulation of T cells (CD27, CD28, ICOS), and genes associated with other immune processes, including Type I IFN response (TNF, TNFSF10), as well as T cell exhaustion (CTLA4)." (PMID 36698398, 2022). "The coligand of CTLA4 and CD28 is B7, which is expressed in APCs and tumor cells." (PMID 36042469, 2022). "Co-expressing 4-1BBL and CD28 could recruit the host immune response against the tumor through the IRF7/IFN-β pathway." (PMID 35903099, 2022). "Multiple studies provide convincing evidence that antigen-dependent co-stimulation through CD28-targeting bispecific T-cell engager antibodies is an effective strategy to specifically increase T-cell activation in vitro and enhance anti-tumor activity in vivo." (PMID 36405686, 2022). "Finally, we have investigated the cross-reactivity and function of murine PMN-MDSC isolated from tumor-bearing mice to inhibit the activation of human T cells activated using CD3/CD28 beads." (PMID 36551639, 2022). "The particles could directly stimulate activated tumor antigen-specific T cells by binding to the T cell receptor and CD28, and activated T cells suppress tumor growth by killing tumor cells expressing the same antigen." (PMID 35890175, 2022). "It is activated with the help of a second signal, the B7-CD28 molecule, which triggers the release of perforin that creates pores in the membranes of target cells (tumor cells), allowing granzymes to enter the cell and degrade the DNA, killing the tumor cells." (PMID 35296094, 2022). "In addition to binding CD3 on T-cells and CD38 on tumor cells, the trispecific binds CD28, which serves as both co-stimulation for T-cell activation and an additional tumor target." (PMID 35768621, 2022). "In a subsequent article, the same humanized anti-CAIX/CD28 lentivector was adapted to secrete anti-PD-L1 IgG1 or IgG4 antibodies into the tumor milieu, which led to a remarkable reduction of T cell exhaustion and improved antitumor persistence in an orthotopic model of ccRCC in NSG mice." (PMID 35628256, 2022). "For instance, tumor targeting CD28 bispecific antibody, which had small side effects, could enhance the antitumor efficacy of PD-1 immunotherapy, prolonging antitumor immunity." (PMID 35571564, 2022). "In mice treated with Imprime, a significantly higher percentage of CD8 T cells expressed both Ki67 and GrzB, and when isolated and stimulated with anti-CD3/CD28 monoclonal Abs, exhibited enhanced proliferation and production of critical anti-tumor effector cytokines IFN-γ, IL-2, and TNF-α." (PMID 35692755, 2022).
tumor (continued). "T25 exhibited increased expression of PD-1, CTLA4 and low expression of CCR7, CD45RA, CD127 and CD28, consistent with previous studies that a subset of tumor-reactive CD8+ TILs were positive for CD103 and CD39 and exhibited an exhausted tissue-resident memory phenotype." (PMID 36311750, 2022). "Conversely, PD-L1 formed on the surface of HCC cells can not only bind to PD-1, but also bind to B7.1 on dendritic cells (DCs) to prevent the interaction of B7.1/CD28 to inhibit the activation of anti-tumor T cells, thereby evading T encirclement and suppression of cells." (PMID 34745958, 2021). "Moreover, studies have indicated superior tumor eradication and increased persistence in vivo when CD28 and 4-1BB domains are combined in a CD19 CAR." (PMID 34885176, 2021). "Using repetitive stimulation assays to model tumor-induced exhaustion, we found that pCAR T cells with specificity for a single or multiple targets consistently outperformed other dual co-stimulatory systems or 2G CARs that contain either 41BB or CD28 alone." (PMID 35028604, 2021). "Indeed, further studies showed that interaction between CD28+MM cells and B7+DCs led to decreased tumor cell apoptosis and production of pro-MM survival and immunosuppressive signals such as IL-6 and indolamine-2,3-dioxygenase (IDO), respectively." (PMID 34439244, 2021). "Costimulation with CD28 or 4-1BB can increase anti-tumor activity." (PMID 34208157, 2021). "The third generation CAR are endowed with co-stimulatory domains in tandem (i.e., CD28 in combination with 4-1BB), which may increase T cell expansion and anti-tumor functions." (PMID 33450862, 2021). "The costimulatory molecule cluster of differentiation (CD) 80, which can be expressed on antigen-presenting cells (APCs) or tumor cells, interacts with both costimulatory (CD28) and coinhibitory (cytotoxic T-lymphocyte antigen 4 (CTLA-4)) receptors and regulates the immune response." (PMID 33923750, 2021). "In a cancer animal model, PD1-1 blockade did not restore anti-tumor T cell function in presence of CD28 blocking antibodies, linked to a tumor growth similar to the not-treated control group." (PMID 33923463, 2021). "Upregulation of PD-L1 on DCs was seen after contact with CD40L:CD28 CSP-expressing T cells suggesting that reprogramming of tumor-conditioned myeloid cells together with checkpoint inhibition could be the next step forward to improve cancer immunotherapy." (PMID 34912334, 2021). "Similarly, an HER-2-directed CD28.CD3ζCAR design expressed by NK92 cells also demonstrated anti-tumor activity against breast cancer, both in vitro and in vivo." (PMID 34072732, 2021). "We show that PDI-1 is a potent competitive inhibitor of PD-1/PD-L1 binding and suppresses tumor growth in vivo through a mechanism involving inhibition of TCR/CD28-dependent signaling, enhancement of anti-tumor cytotoxicity, and increased inflammatory cytokine production." (PMID 34054817, 2021). "Reports of the expression of CTLA-4 and CD28 in tumor-infiltrating NK cells suggest that further efforts are needed to assess whether the NK cell-specific effects of anti-CTLA-4 blockade have been misattributed to T cells." (PMID 33468555, 2021). "However, in the later stage Teff, persistent recurrent exposure of the immunogenic tumor antigens leads to a gradual loss of the expression of CD27 and CD28, converting DP cells to DN cells." (PMID 34593620, 2021). "Our robust preclinical evaluation of second-generation CAR T cell designs indicate that CD28 signaling may produce more potent candidates to treat solid tumors because they more effectively migrate to and expand at the tumor site." (PMID 33801448, 2021). "In light of the fact that adenosine generated via CD73 suppresses anti-tumor effector T cell function, these findings suggest that providing sufficient CD28 signaling in the tumor microenvironment can inhibit CD73 expression on CD8+ T cells thereby promotes anti-tumor immunity." (PMID 34011962, 2021).
tumor (continued). "We hypothesized that co-expression of separate chimeric receptors in which both CD28 and 41BB were positioned next to the plasma membrane would provide dual tumor antigen-dependent co-stimulation, thereby mitigating tumor-induced CAR T cell dysfunction." (PMID 35028604, 2021). "In addition, our findings confirm that CD28 bispecific antibodies can enhance the anti-tumor efficacy of treatment with CD3 bispecific antibodies." (PMID 34852825, 2021). "To test whether parallel placement of CD28 and 41BB co-stimulatory domains in membrane-proximal positions would yield synergistic signaling, we first evaluated the in vitro anti-tumor activity of pCAR 34/M T cells." (PMID 35028604, 2021). "We showed for both CAR specificities that T cells with the CD28 co-stimulatory endodomain migrated better to the tumor and had superior anti-tumor effect, while T cells with 4-1BB co-stimulus (except HER2-SS-4-1BB/ζ) failed to expand at the tumor site and induce tumor regression." (PMID 33801448, 2021). "Likewise, ROS that is induced upon TCR and CD28 activation was found to be increased in tumor-infiltrating Treg cells compared to their splenic counterparts." (PMID 34539668, 2021). "Tumor-infiltrating MAIT cells were readily stimulated by anti-CD3/CD28 treatment to express CD25." (PMID 33885944, 2021). "We next investigated whether CD28 co-stimulation confers superior anti-cancer activity against another tumor entity and antigen." (PMID 33801448, 2021). "Thus, CaP coating on the Ti sample promoted the in vitro survival of CD4+ subsets of tumor-derived Jurkat T cells activated by anti-CD2/CD3/CD28 antibodies." (PMID 34279263, 2021). "CD40L:CD28 CSPs are a new type of switch proteins designed to exert dual beneficial antitumor effect by acting directly on the gene-modified T cells and simultaneously on tumor cells and tumor-supporting cells of the TME." (PMID 34912334, 2021). "In the TME TCR/CD28 signaling seems also to denominate Treg stability and promote tumor growth." (PMID 34539668, 2021). "Although Mel enhances B7 expression on tumor cells, which leads to engagement of tumor reactive T cells, it has been known for some time that MM cells can also express CD28 and that the level of expression correlates with disease progression and poor prognosis." (PMID 34439244, 2021). "We hypothesize that superior T cell expansion combined with the faster and stronger cytokine response characteristic for CD28-incorporating second-generation CAR T cells produces sufficiently high cytokine levels to destroy tumor stroma." (PMID 33801448, 2021). "CAR constructs are composed of (i) the single-chain variable fragment (scFv) of tumor antigen-specific Ab (Ab), (ii) a hinge region, (iii) the hydrophobic trans-membrane domain which is usually derived from CD8α or CD28 and (iv) the intracellular signaling moieties." (PMID 32707982, 2020). "However, second-generation ICOS-based CAR showed to increase the anti-tumor activity and persistence of the transduced T cells when compared to CARs with CD28 and 4-1BB intracellular-domains." (PMID 33374128, 2020). "Furthermore, to convert tumor PD-L1 to a ligand that transmits CD28 and 4-1BB costimulatory signals to effector T cells, we generated another combinatorial antigen receptor, PD-1-CD28-4-1BB activating chimeric receptor (PD1ACR)." (PMID 32637575, 2020). "A long list of studies employing CARs with a CD28 signaling domain reported potent and quick anti-tumor effector functions but found these to be rather short-lived and associated with limited cell persistence in vivo when compared to, e.g., the 4-1BB signaling domain." (PMID 32429316, 2020). "Upon stimulation, STAT3 pathway is activated and the CAR T-cells show potent cytotoxic activity even after repetitive antigen stimulation in vitro resulting in a superior anti-tumor effect in vivo when compared to T cells transduced with a CD28 or 4-1BB second-generation CAR." (PMID 33374128, 2020).